HNRNPK (heterogeneous nuclear ribonucleoprotein K)
Diseases named in the same sentence as HNRNPK in open-access papers (continued):
Sharing a sentence is not in itself a finding about the gene and the disease.
melanoma (8 papers, 2015 to 2025). A malignant, usually aggressive tumor composed of atypical, neoplastic melanocytes. "Collectively, these data suggest loss of hnRNPK or overexpress of Fbxo4 is sufficient to significantly suppress spontaneous lung colonization of B16F10 melanoma cells in vivo." (PMID 36329064, 2022). "Consistently, our mechanistic studies demonstrate that loss of Fbxo4 increases cell motility, cell invasion, and melanoma metastasis in an hnRNPK- and c-Myc-dependent manner." (PMID 36329064, 2022). "Consistent with observations in Fbxo4-deficient MEFs, Fbxo4-I377M melanoma cell lines exhibited increased capacity for invasion relative to melanoma cell lines with Fbxo4;wt this invasive phenotype was dependent on expression of hnRNPK." (PMID 36329064, 2022). "Therefore, the inactivation or loss of Fbxo4 that occurs in melanoma and esophageal cancer unleashes cytoplasmic hnRNPK activity, unmasking malignant function though dysregulated translation of multiple mRNA targets that promote tumor progression." (PMID 36329064, 2022). "Consistent with our findings, hnRNPK down‐regulation by a mitogen‐activated extracellular signal‐regulated kinase kinase inhibitor increased the radiotherapy sensitivity in malignant melanoma cells." (PMID 27862976, 2017). "The splicing factor hnRNPK drives a splicing switch of AKT2 (isoform 210 to 206), restoring kinase hyperactivity via retention of the A-loop fragment and conferring MAPK-targeted therapy resistance in melanoma through PI3K-AKT pathway activation." (PMID 40681872, 2025). "Collectively, our results demonstrate that the hnRNPK-regulated splicing program represents a novel mechanism driving MAPK pathway inhibitor resistance, providing translational insights for targeting splicing-mediated kinase rewiring in refractory melanoma." (PMID 40681872, 2025).
glioblastoma (6 papers, 2021 to 2026). The most malignant astrocytic tumor (WHO grade IV). "In this study, we investigated the expression of SUMO-modified related molecules in glioblastoma and the role of HNRNPK in SUMO modification." (PMID 39494331, 2024). "Previous studies have also demonstrated that FGD5-AS1 activates the Wnt/β-catenin signaling pathway by regulating the miR-129-5p/HNRNPK axis, thus promoting the progression of glioblastoma." (PMID 38613802, 2024). "SUMOylation of the K422 residue of HNRNPK interferes with its DNA binding ability, thereby disrupting downstream transcription, and ultimately leading to transitions between different states of glioblastoma stem cells." (PMID 39494331, 2024).
glioma (6 papers, 2015 to 2025). A benign or malignant brain and spinal cord tumor that arises from glial cells (astrocytes, oligodendrocytes, ependymal cells). "We validated the interaction of hnRNPK and RTVP-1 by co-immunoprecipitation and showed that hnRNPK was associated with N-WASP also in glioma cells." (PMID 26305187, 2015). "Thus, low levels of hnRNPK in glioma cells was associated with increased cell migration and invasion." (PMID 26305187, 2015). "Thus, hnRNPK is expressed in low levels in glioma and its low expression is associated with increased migration and invasion." (PMID 26305187, 2015). "Silencing the expression of AGPS in glioma cells can downregulate HNRNPK, which proves the correlation between the two expressions." (PMID 34621897, 2021). "HNRNPK plays an important role for glioma in proliferation, migration, invasion, and apoptosis in previous reports." (PMID 34621897, 2021). "We found that overexpression of hnRNPK inhibited glioma cell spreading and migration, whereas silencing of hnRNPK induced the opposite effect." (PMID 26305187, 2015). "Our conclusion was further validated by demonstrating that overexpression of RTVP-1 was able to abrogate the inhibitory effect of hnRNPK on N-WASP-induced glioma cell migration." (PMID 26305187, 2015). "Since hnRNPK inhibits cell migration in glioma cells, we examined its expression in the different GBM specimens." (PMID 26305187, 2015). "Overexpression of hnRNPK decreased the gelatin degradation of the U87 glioma cells, whereas overexpression of N-WASP induced the opposite effect." (PMID 26305187, 2015). "We found that overexpression of RTVP-1 significantly reduced the association of N-WASP and hnRNPK and abrogated the inhibitory effect of hnRNPK on N-WASP-induced cell migration when co-expressed in the A172 glioma cells." (PMID 26305187, 2015). "Overexpression of hnRNPK induced an inhibitory effect on cell spreading and migration of glioma cells whereas its silencing induced opposite effects." (PMID 26305187, 2015). "hnRNPK decreased cell migration, spreading and invasion in glioma cells." (PMID 26305187, 2015). "We then examined the expression and function of hnRNPK in glioma cells." (PMID 26305187, 2015). "We then examined the effects of hnRNPK on glioma cell spreading, migration and invasion." (PMID 26305187, 2015). "Based on the interaction of both RTVP-1 and hnRNPK with N-WASP and their opposite effects on glioma cell spreading, migration and invasion we speculated that RTVP-1 might compete with hnRNPK for the association with N-WASP." (PMID 26305187, 2015). "Using co-immunoprecipitation we validated the interactions of hnRNPK with N-WASP and RTVP-1 in glioma cells." (PMID 26305187, 2015). "In summary, we report that RTVP-1 regulates glioma cell spreading, migration and invasion and that these effects are mediated via interaction with N-WASP and by interfering with the inhibitory effect of hnRNPK on the function of this protein." (PMID 26305187, 2015). "In summary, we report that RTVP-1 regulates glioma cell spreading, migration and invasion and that these effects are mediated via interaction with N-WASP and by interfering with the inhibitory effect of hnRNPK on the function of N-WASP." (PMID 26305187, 2015). "Since hnRNPK was identified as a potential interacting protein of RTVP-1 using the pull-down assay, we first validated the interaction of these two proteins using reciprocal co-immunoprecipitation in glioma cells and GSCs." (PMID 26305187, 2015). "Transcriptional regulators of HNRNPK such as brain-derived neurotrophic factor (BDNF) were upregulated in gliomas, and we hypothesized that the AGPS-HNRNPK complex could facilitate to regulate tumor-related mRNA by BDNF, which would be explored in further study." (PMID 34621897, 2021).
liver cancer (6 papers, 2006 to 2025). An epithelial or non-epithelial malignant neoplasm that arises from the liver. "Conversely, the tumor suppressor gene encoding protein PTEN forms a complex with hnRNPK to inhibit its activity, and shearing of G6PD precursor RNA inhibits liver cancer." (PMID 35352475, 2022). "In this study, we found that snoRD126 binds to hnRNPK and regulates FGFR2 expression, promoting the development of liver cancer." (PMID 33891563, 2021).
lymphoma (5 papers, 2012 to 2024). A malignant (clonal) proliferation of B- lymphocytes or T- lymphocytes which involves the lymph nodes, bone marrow and/or extranodal sites. "Moreover, hnRNPK induced defects in growth and development of mice, resulting in their increased susceptibility to hematological malignancies and lymphoma." (PMID 35352475, 2022).
osteosarcoma (5 papers, 2019 to 2023). A usually aggressive malignant bone-forming mesenchymal neoplasm, predominantly affecting adolescents and young adults. "In this context, it should be noted that the S379A and S379D mutations of hnRNPK in U2OS osteosarcoma cells have also been found to have the same influence on cell migration." (PMID 31110205, 2019). "Among the top DEPs identifying fibroblastic groups from other pathological subtypes are POSTN, TPM4, RTN4, HNRNPK, and RACK1, which were directly associated with osteosarcoma progression and prognosis." (PMID 37681913, 2023). "Arginine methylation of HNRNPK was shown to suppress the apoptosis of U2OS osteosarcoma cells by interfering with the DDX3-hnRNPK interaction." (PMID 37681913, 2023). "We previously showed that arginine methylation of hnRNPK attenuated the apoptosis of U2OS osteosarcoma cells under DNA damage conditions, whereas the replacement of endogenous hnRNPK with a methylation-defective mutant inversely enhanced apoptosis." (PMID 34575922, 2021). "It has been reported that the interaction between DDX3X and hnRNPK could play a pro-apoptotic role in U2OS osteosarcoma cells under DNA-damage conditions." (PMID 37149668, 2023). "Moreover, the interaction between DDX3X and hnRNPK could play a pro-apoptotic role in U2OS osteosarcoma cells under DNA-damage conditions." (PMID 37149668, 2023).
cervical carcinoma (4 papers, 2021 to 2025). A carcinoma arising from either the exocervical squamous epithelium or the endocervical glandular epithelium. "The knockdown of heterogeneous nuclear ribonucleoprotein K (hnRNPK) eventually reduced PTOV1-AS1 expression in HeLa cervical carcinoma cells." (PMID 34440306, 2021). "Combined with the existing reports and the results of RNA-seq alternative splicing analysis, it is speculated that GBP1 may regulate the alternative splicing of CD44 protein by binding to interacting protein-HNRNPK, and thus play a role in promoting cancer in cervical cancer." (PMID 38167153, 2024). "In cervical cancer, GBP1, after binding to HNRNPK, regulates CD44 protein expression through alternative splicing at the 3′ splice site, ultimately playing a cancer-promoting role." (PMID 40018406, 2025). "That is, GBP1, after binding with HNRNPK, regulates the expression of CD44 protein through A3SS alternative splicing form, and finally plays a cancer-promoting role in cervical cancer." (PMID 38167153, 2024).
lung adenocarcinoma (4 papers, 2016 to 2023). A carcinoma that arises from the lung and is characterized by the presence of malignant glandular epithelial cells. "We found that HNRNPK was highly expressed in cancer patients of lung adenocarcinoma (LUAD) and lung squamous cell carcinoma (LUSC) (p-values < 0.001 for Wilcoxon’s rank sum test)." (PMID 36681772, 2023). "The results showed that hnRNPK was highly overexpressed in both the nucleus and cytoplasm of lung adenocarcinoma cells as compared with normal tissues, whereas the phospho-GSK3β was mainly located in the cytoplasm which was significantly downregulated in the tumor tissues." (PMID 26972480, 2016). "In this study, we show that, when H1299 lung adenocarcinoma cells are treated with TRAIL, hnRNPK is translocated from nucleus to cytoplasm where it interacts and co-localizes with GSK3β." (PMID 26972480, 2016). "Our finding is corroborated by our immunohistochemical analysis with tissue microarray demonstrating the negative correlation between hnRNPK expression level and that of the Ser9-phsphorylated GSK3β in lung adenocarcinoma tissues." (PMID 26972480, 2016). "Our immunohistochemical analysis using tissue microarray provides the clinical evidence of this finding by establishing a negative correlation between the level of hnRNPK expression and the Ser9 phosphorylation of GSK3β in both lung adenocarcinoma tissues and normal tissues." (PMID 26972480, 2016).
oral cancer (4 papers, 2015 to 2022). "A study involving a proteomics-based approach identified numerous protein markers, namely prothymosin alpha (PTMA), S100A7, 14-3-3ζ, 14-3-3δ, hnRNPD, and hnRNPK, used for distinguishing between normal mucosa, dysplasia, and oral cancer." (PMID 35741145, 2022). "In this respect, we observed other members of the hnRNP family including hnRNPA2/B1, hnRNPK, hnRNPU, hnRNPG forming heterodimers with hnRNPD in oral cancer cells." (PMID 26318153, 2015). "Both hnRNPK and 14-3-3ζ were identified in as interaction partners of hnRNPD in oral cancer cells and tissues." (PMID 26318153, 2015). "Using similar approach, we verified the interaction of hnRNPD with hnRNPK and S100A9 in oral cancer cells." (PMID 26318153, 2015).
tauopathies (4 papers, 2022 to 2025). "Knock-down of HNRNPK in SH-SY5Y neuroblastoma cells resulted in similar splicing defects that are present in FTLD human brain tissue, suggesting that the accumulation of HNRNPs in tauopathy may result in loss of function." (PMID 36253823, 2022). "This suggests that not all HNRNPs have the same actions in tauopathy and lends weight to the hypothesis that HNRNPK, HNRNPA1 and HNRNPA2/B1 may influence the development of early tau pathology." (PMID 36253823, 2022).
triple-negative breast carcinoma (4 papers, 2019 to 2024). An invasive breast carcinoma which is negative for expression of estrogen receptor (ER), progesterone receptor (PR), and human epidermal growth factor receptor 2 (HER2). "Our study revealed that the LINC00571/HNRNPK/ILF2/IDH2 axis promoted the progression of triple-negative breast cancer by regulating tricarboxylic acid cycle metabolites." (PMID 38238853, 2024). "This study aims to investigate the unexplored functions of hnRNPK S379 phosphorylation using MDA-MB-231 cells, a triple negative breast cancer cell that has amplification of the Aurora-A kinase gene." (PMID 31110205, 2019).
atherosclerosis (3 papers, 2021 to 2025). A disease characterized by the build-up of fatty material and calcium deposition in the arterial wall resulting in partial or complete occlusion of the arterial lumen. "Combined with the observations from the present study, this suggests that HNRNPK may be involved in atherosclerosis among patients with diabetes." (PMID 34496837, 2021).
Cognitive impairment (3 papers, 2016 to 2025). Abnormal cognition is characterized by deficits in thinking, reasoning, or remembering. "Moreover, Mrgx, the mouse orthologue of MORF4L2 (aka MRGX, MIM 300409) has been shown to interact with HNRNPK, a gene known to be associated cognitive impairment." (PMID 27506666, 2016).
diabetes (3 papers, 2021 to 2025). "We believe that the interaction between FOXO1 and hnRNPK may be involved in the regulation of the expression of a large group of genes and play certain roles in cancer and diabetes." (PMID 36964488, 2023).
Ewing sarcoma (3 papers, 2016 to 2020). A small round cell tumor that lacks morphologic, immunohistochemical, and electron microscopic evidence of neuroectodermal differentiation. "In this study, by employing multiple approaches, we have now identified several splicing factors (SRSF1, SRSF3, and SRSF10, hnRNPK, hnRNPM, and FUS) as regulators of DHX9 splicing in Ewing sarcoma cells." (PMID 32023846, 2020). "Interestingly, there is a marked overlap in hnRNPK-repressed genes and those repressed by EWSAT1, suggesting that hnRNPK and EWSAT1 act together to repress the expression of a subset of target genes in the context of Ewing sarcoma." (PMID 30658384, 2019).
fibrosarcoma (3 papers, 2015 to 2021). A malignant mesenchymal fibroblastic neoplasm affecting the soft tissue and bone. "In a recent study it was shown that the nuclear level of hnRNPK is reduced in progressive murine fibrosarcoma compared to regressive tumors." (PMID 26305187, 2015).
Intellectual disability (3 papers, 2016 to 2023). "De novo truncating variants in HNRNPK have been shown to cause Au-Kline neurodevelopmental syndrome including intellectual disability, ADHD, speech impairment, cardiac anomalies and a variety of dysmorphic features." (PMID 36117209, 2023).
Kabuki syndrome (3 papers, 2016 to 2025). Kabuki syndrome (KS) is a multiple congenital anomaly syndrome characterized by typical facial features, skeletal anomalies, mild to moderate intellectual disability and postnatal growth deficiency. "We validated a novel de novo HNRNPK intronic variant (c.1192-3 C>A, p.Leu398ValfsTer21) in a patient previously misdiagnosed with Kabuki Syndrome (KS)." (PMID 40304117, 2025). "HNRNPK has an important role in chromatin remodelling and all genes known to cause Kabuki syndrome are chromatin regulators." (PMID 26954065, 2016). "Facial dysmorphism and multiple congenital anomalies (cardiac, renal and orofacial clefting) overlap with Kabuki syndrome and hence LoF variants in HNRNPK should be considered as a molecular basis for patients with Kabuki‐like syndrome." (PMID 26954065, 2016). "This might explain the phenotypic overlap seen between Kabuki syndrome and HNRNPK mutations." (PMID 26954065, 2016). "Recent studies have identified additional genes associated with Kabuki syndrome, including RAP1A, RAP1B, and HNRNPK." (PMID 38667491, 2024). "Thus, a comprehensive screening of other genes associated with Kabuki syndrome (e.g., KDM6A, RAP1A, RAP1B, and HNRNPK) was not performed." (PMID 38667491, 2024).
pancreatic ductal adenocarcinoma (3 papers, 2022 to 2024). An infiltrating adenocarcinoma that arises from the epithelial cells of the pancreas. "CircFOXK2 promoted pancreatic ductal adenocarcinoma (PDAC) progression by interacting with YBX1 and hnRNPK proteins to upregulate the expression of NUF2 and PDXK oncogenes." (PMID 38890620, 2024). "Recently, a circRNA derived from FOXK2 (has_circ_0000816) has been found to promote the growth and metastasis of pancreatic ductal adenocarcinoma by sponging miR-942 and directly binding YBX1 and hnRNPK." (PMID 36922872, 2023).
skin carcinoma (3 papers, 2017 to 2023). "Keratins are an interaction platform for various proteins and a previous study showed that keratin closely related to K19, K17, interacts with HNRNPK in skin cancer cells." (PMID 37592256, 2023). "A previous study in skin cancer cells showed that a cytoskeletal protein keratin 17 (K17) is required for the cytoplasmic localization of HNRNPK, demonstrating that keratin is a regulator of HNRNPK localization." (PMID 37592256, 2023).
asthma (2 papers, 2022 to 2025). "The GSE147878 dataset further validated that genes other than RPL17 and HNRNPK were key genes regulating severe asthma." (PMID 35645813, 2022).